STAT2 (signal transducer and activator of transcription 2)
Diseases named in the same sentence as STAT2 in open-access papers (continued):
Sharing a sentence is not in itself a finding about the gene and the disease.
oral cancer (4 papers, 2020 to 2023). "The prognostic values of CXCL10 and STAT2 are confirmed in another validation cohort (GSE65858) that contains 83 oral cancer cases." (PMID 35207629, 2022). "A recent meta-study found that increased tumor infiltration with Th1 and CD8+ T cells was associated with the expression status of STAT2 and its target CXCL10, suggesting that the activation of this pathway could predict the outcome in oral cancer patients." (PMID 38001683, 2023). "GSEA of oral cancers stratified by CXCL10/STAT2 expression showed that activation of T-cell pathways and increased tumor infiltration scores of Type 1 T helper (Th1) and CD8+ T cells were associated with high CXCL10/STAT2 expression." (PMID 35207629, 2022). "In addition, the expressions of CXCL10 and STAT2 in oral cancer were also correlated in TCGA (r = 0.677, p < 0.001) and GSE65858 (r = 0.617, p < 0.001) cohorts." (PMID 35207629, 2022). "Phosphorylated STAT2 induces the proliferation of oral cancer cells." (PMID 33330624, 2020). "High expressions of CXCL10 and STAT2, which are correlated with activation of T-cell pathways and tumor infiltration of Th1 and CD8+ T cells, are good prognostic biomarkers for oral cancer patients." (PMID 35207629, 2022). "After validating in another oral cancer cohort (GSE65858), high expressions of C-X-C motif chemokine ligand 10 (CXCL10) and Signal transducer and activator of transcription 2 (STAT2) were confirmed to be good prognostic biomarkers." (PMID 35207629, 2022). "The prognostic values of the core enriched genes in interferon-α/γ pathways were examined in TCGA data set and were validated in another oral cancer cohort (GSE65858), which resulted in CXCL10 and STAT2." (PMID 35207629, 2022). "It is worth specifically examining the biomarker role of CXCL10/STAT2 in responses to anti-EGFR and ICB-based therapies in oral cancer patients." (PMID 35207629, 2022). "This study extracts 342 and 83 oral cancer data from TCGA HNSC and GSE65858 (270 head and neck cancers), respectively, and then can demonstrate a significant correlation between good patient OS and high STAT2 expression in both cohorts." (PMID 35207629, 2022). "This discrepancy suggests that STAT2 is a prognostic biomarker for patients with oral cancer but not with other types of head and neck cancers." (PMID 35207629, 2022). "Although the clinical information is not publicly available for these 4 oral cancer data sets, it is possible that the patients with high CXCL10/STAT2 expression also have a more favorable outcome than those with low CXCL10/STAT2 expression." (PMID 35207629, 2022).
Sepsis (4 papers, 2016 to 2024). Sepsis is defined as life-threatening organ dysfunction caused by a dysregulated host response to infection. "Other aspects of STAT2 deficiency are unexplained, though, such as the exacerbation of experimental sepsis observed with STAT2-deficient mice, given that genetic deletion of other components of type 1 IFN signaling results in the opposite phenotype, namely protection against sepsis." (PMID 27780205, 2016). "Moreover, the downstream TFs targeted by the LR pairs in sepsis-induced ARDS are FOS, RB1, STAT2, and STAT3." (PMID 35222683, 2022). "Furthermore, we analyzed the downstream TFs targeted by LR pairs and found that different TFs, including SMAD3, RBPJ, and MAX, were targeted in sepsis-only patients, while FOS, STAT3, STAT2, and RB1 were targeted in sepsis-induced patients." (PMID 35222683, 2022).
Alzheimer disease (3 papers, 2021 to 2026). A progressive, neurodegenerative disease characterized by loss of function and death of nerve cells in several areas of the brain leading to loss of cognitive function such as memory and language. "For instance, STAT2 regulates Sirt4 transcription and activates the mTOR pathway, thereby promoting neuronal apoptosis in Alzheimer’s disease." (PMID 41523985, 2026). "The comparisons of postmortem aged brain specimens revealed reduced ACE2, TMPRSS2, but elevated STAT2 protein levels in individuals with DS and Alzheimer’s disease (DS-AD) compared to control and Alzheimer’s disease (AD) group." (PMID 40445428, 2025). "In summary, this study we have also identified important genes (NRG1, NEDD9, IRF5, IFI35, STAT1, STAT2, JAK2, IL3RA), and alterations in biological processes and pathways that may be associated with Alzheimer’s Disease." (PMID 34484988, 2021).
asthma (3 papers, 2020 to 2024). "Due to the dramatic skewing of the Th1/Th2 axis in the presence of hSTAT2, we hypothesize that antagonism of STAT2 by HMPV in human infection may contribute to the association of HMPV and asthma in susceptible individuals." (PMID 32635475, 2020).
B-cell lymphoma (3 papers, 2015 to 2025). "Loss of the STAT2-IFNα/β axis confers resistance to apoptosis induced by chemotherapeutic drugs in B-cell lymphoma cell lines." (PMID 26654227, 2015). "The STAT2/type I interferon (IFNα/β) axis is well known to have a tumor suppressor function in B-cell lymphoma in vitro and inhibits tumor growth in vivo." (PMID 26654227, 2015). "STAT3 inhibition also synergized with inducers of type I IFN, a downstream effector of the cGAS-STING pathway, to effectively inhibit B cell lymphoma growth, possibly by alleviating the suppressive effects of STAT3 on IRF7, IRF9, STAT1, and STAT2 expression." (PMID 40743845, 2025). "Next, we compared transcript levels of STAT1, STAT2 and other Type I IFN signaling components in normal B cells (MYCLOW), pre-lymphoma B cells from Eμ-MYC mice (MYCHIGH), and overt B-cell lymphoma from Eμ-MYC mice (MYCHIGH), a mouse model of MYC-driven B-lymphoma (GSE5101140)." (PMID 32503978, 2020).
co-infection (3 papers, 2017 to 2025). "Interestingly, in murine influenza and MRSA co-infection, STAT2 is important in macrophage polarization, where STAT2-deficient mice had improved bacterial burden, potentially caused by an increased number of M1 macrophages." (PMID 33542723, 2020). "Therefore, we analyzed the differential expression of STAT family genes and found that HIV-mono infection leads to the upregulation of STAT3 and STAT4, whereas co-infection results in the upregulation of STAT1 and STAT2." (PMID 41394852, 2025).
Encephalopathy (3 papers, 2018 to 2025). Encephalopathy is a term that means brain disease, damage, or malfunction. "Together with the STAT2 signaling pathway, the TGF-β signaling pathway can inhibit the progression of autoimMune encephalopathy." (PMID 30345171, 2018).
fibrosarcoma (3 papers, 2011 to 2023). A malignant mesenchymal fibroblastic neoplasm affecting the soft tissue and bone. "To test whether STAT2 interferes with STAT1 DNA binding, we used electrophoretic mobility shift assays (EMSAs) with extracts from STAT2-deficient human U6A fibrosarcoma cells and stable derivatives expressing WT STAT2 or mutant STAT2-L82A." (PMID 27780205, 2016).
glioblastoma (3 papers, 2023 to 2026). The most malignant astrocytic tumor (WHO grade IV). "Among the candidate miRNAs, miR-221 has been shown to regulate the expression levels of STAT1 and STAT2 in glioblastoma cells." (PMID 37864270, 2023).
HIV-1 infection (3 papers, 2013 to 2020). The type species of lentivirus and the etiologic agent of acquired immunodeficiency syndrome (AIDS). "Therefore, it would be interesting to investigate how USP18 impacts IFN-I signaling regulation during HIV-1 infection, and whether STAT2 and/or IRS-4 are involved." (PMID 31658294, 2019). "Investigations on the phosphorylation status of STAT1, STAT2 and IRF9 in chronic HIV-1 infection are underway." (PMID 33064743, 2020).
liver fibrosis (3 papers, 2017 to 2024). "Collectively, these findings suggested that the causal role of Fendrr in liver fibrosis is associated with its interaction with STAT2, which promotes the induction of IL-6 and activation of HSC in a paracrine manner." (PMID 38762176, 2024). "In another study characterizing molecular changes associated with early hepatic fibrosis, STAT2/IRF9 expression was found to be increased in diseased livers of patients with hepatic fibrosis, compared with healthy control livers." (PMID 36671504, 2023). "Accordingly, disrupting the interaction between Fendrr and STAT2 by ectopic expression of a STAT2 mutant attenuated the profibrotic response inspired by Fendrr in the CCl4-induced liver fibrosis." (PMID 38762176, 2024). "As expected, the ectopic expression of STAT2-Mut1 abolished the Fendrr-mediated increase of serum IL-6 in CCl4-treated mice and greatly suppressed the profibrotic effect of Fendrr on liver fibrosis." (PMID 38762176, 2024). "H&E, sirius red staining, and immunostaining of Col I and α-SMA, as well as hepatic hydroxyproline content assay, revealed that ectopic expression of STAT2-Mut1 protected the mice from liver fibrosis." (PMID 38762176, 2024). "Based on these observations, we further overexpressed STAT2-Mut1 in vivo and showed the inhibitory effects on Fendrr-mediated liver fibrosis." (PMID 38762176, 2024). "We then tested whether overexpression of STAT2-Mut1 would prevent CCl4-induced liver fibrosis in mice by intravenously injecting the lentivirus 2 days prior to the first injection of CCl4." (PMID 38762176, 2024). "Our results clearly revealed a failure to upregulate STAT2 and IRF7 in HCV/CMV co-infected patients with high grades of liver fibrosis when compared to HCV mono-infected patients." (PMID 28871140, 2017).
lymphoma (3 papers, 2020 to 2024). A malignant (clonal) proliferation of B- lymphocytes or T- lymphocytes which involves the lymph nodes, bone marrow and/or extranodal sites. "Various experimental evidence strongly suggests that STAT2 plays a significant role in carcinogenesis, including lymphomas, which Sjögren’s disease patients are known to have a heightened risk of developing." (PMID 38790257, 2024). "We observed a significant suppression of STAT1 and STAT2 levels, and a reduction in total and activated NK cell subsets in T-lymphoma patients in comparison to their normal counterparts." (PMID 32503978, 2020).
rheumatoid arthritis (3 papers, 2019 to 2022). A chronic, systemic autoimmune disorder characterized by inflammation in the synovial membranes and articular surfaces. "Transcription factors STAT1 and STAT2 are activated by interferons and are common targets in studies of potential therapeutics for OA and rheumatoid arthritis." (PMID 35299636, 2022). "It reported that STAT2 and JAK/STAT pathway (osteoclast differentiation pathway) were closely associated with cartilage relevant diseases, such as osteoarthritis (OA) cartilage or in human articular chondrocyte mechanotransduction, the bovine intervertebral disc, and rheumatoid arthritis (RA)." (PMID 31191668, 2019).
adenovirus infection (2 papers, 2015 to 2018). "This novel hamster model, along with the STAT2 KO model that we developed, may be useful for dissecting the contributions of adaptive immunity and innate immunity to the control of adenovirus infections and possibly for other pathogens in humans." (PMID 29734775, 2018).
autoimmune disease (2 papers, 2022 to 2025). A disorder resulting from loss of function or tissue destruction of an organ or multiple organs, arising from humoral or cellular immune responses of the individual to their own tissue constituents. "All STAT family members (STAT1, STAT2, STAT3, STAT4, STAT5A, STAT5B, and STAT6) are related to autoimmune diseases." (PMID 35204186, 2022). "STAT1, STAT2, and IRF9 amplify the JAK-STAT signaling pathway to enhance the IFN response, and the JAK-STAT pathway transduces intracellular signals for various cytokines, which is crucial for the pathogenesis of autoimmune diseases." (PMID 41181153, 2025).
colitis (2 papers, 2013 to 2023). Inflammation of the colon. "In that study, the RNA-sequencing (RNA-Seq) analysis of colon tissue samples from WT and Stat2−/− mice receiving DSS indicated that the deficiency in STAT2 resulted in the downregulation of many genes that are implicated in the pathogenesis of experimental DSS-induced colitis and IBD." (PMID 38001683, 2023). "Very recent data indicated that STAT2 controlled the level of intestinal inflammation in different mouse models of experimental colitis." (PMID 38001683, 2023). "In line with a potential role for STAT2, one study has shown that STAT2 KO mice produce less MCP-1 in a model of colitis." (PMID 23542035, 2013). "However, this canonical pathway by which STAT2-mediated type I IFN signals induce cell death and promote inflammation, as recently reported for experimental colitis, is only one possible outcome." (PMID 38001683, 2023).
Colorectal Tumors (2 papers, 2023 to 2025). "Our findings demonstrate that cell-autonomous STAT2 enhances colorectal tumor growth and correlates with poorer outcomes through mechanisms independent of IFN-I signaling, highlighting STAT2 signaling as a potential therapeutic target in CRC." (PMID 41440237, 2025). "Taken together, the results of the present study suggest that reducing STAT2 signaling in colorectal tumors may potentially boost therapy responses." (PMID 38001683, 2023).
heart failure (2 papers, 2023 to 2025). Inability of the heart to pump blood at an adequate rate to meet tissue metabolic requirements. "Six STAT2-deficient patients died of heart failure in the context of febrile illness without identified pathogen." (PMID 36976641, 2023). "However, no studies have explored the association between STAT2 and macrophage polarization in heart failure." (PMID 40873619, 2025).
liver cancer (2 papers, 2019 to 2024). An epithelial or non-epithelial malignant neoplasm that arises from the liver. "IFIT3 can enhance the anti-liver cancer effect of IFN-α by binding transcriptional activators STAT1 and STAT2." (PMID 38753689, 2024).
multiple sclerosis (2 papers, 2023 to 2025). A progressive autoimmune disorder affecting the central nervous system resulting in demyelination. "In addition, it decreased STAT2-induced IFN-β in a murine model of multiple sclerosis (MS) and PBMCs of MS patients carrying the C allele compared to the G allele." (PMID 37813633, 2023).
pemphigus vulgaris (2 papers, 2020 to 2022). Pemphigus is a group of chronic autoimmune skin diseases characterized by blister formations on the outer layer of the skin and the mucous membranes. "That is why the aim of this study was to evaluate the expression of proteins JAK3, STAT2, STAT4, and STAT6 in skin lesions and perilesional area in patients with pemphigus vulgaris as well as in the control group." (PMID 32170648, 2020). "The aim of this study was to evaluate the expression of proteins: JAK3, STAT2, STAT4 and STAT6 in epithelium lesions in patients with pemphigus vulgaris (PV), bullous pemphigoid (BP), oral lichen planus (LP) and chronic ulcerative stomatitis (CUS), as well as in the control group." (PMID 36613766, 2022).
Salmonella Infections (2 papers, 2019 to 2024). Infections with bacteria of the genus SALMONELLA. "Indeed, recent research has shown that, under experimental settings, an immune-compromised host (through loss of TLR signaling, IL-22 production, or STAT2 signaling) is better equipped to contain Salmonella infection." (PMID 38236896, 2024). "We speculate that STAT2 signaling in colonocytes during Salmonella infection is equally important as in neutrophils for crosstalk and the release of chemokines for the recruitment and activation of neutrophils and macrophages." (PMID 31009517, 2019). "Here we used Stat2-/- mice, which causes the genetic ablation of type I IFN signaling, in combination with the streptomycin pretreated mouse model to pinpoint the role of type I IFNs in host response to Salmonella infection." (PMID 31009517, 2019). "Our study highlights the importance of STAT2 signaling in neutrophils during Salmonella infection." (PMID 31009517, 2019).
skin cancer (2 papers, 2020 to 2022). "Since most studies investigating the role of STAT2 have focused only on skin cancer, the various underlying roles of STAT2 in different cellular contexts have been easy to overlook." (PMID 32973222, 2020). "The role of STAT2 in the tumorigenesis of CRC and skin cancer has also been described." (PMID 36061181, 2022).
skin inflammation (2 papers, 2024 to 2025). "Among these, STAT1 and STAT2 are primarily activated by IFN-γ and other Th1-associated cytokines, contributing to persistent skin inflammation and tissue damage during the chronic phase of AD." (PMID 40724851, 2025). "STAT1 and STAT2 are mainly activated in response to IFN-γ and other Th1-related cytokines and are involved in perpetuating skin inflammation and aggravating tissue damage in the chronic stage of AD." (PMID 39769302, 2024).
small cell lung carcinoma (2 papers, 2022 to 2024). Small cell lung cancer (SCLC) is a highly aggressive malignant neoplasm, accounting for 10-15% of lung cancer cases, characterized byrapid growth, and early metastasis. "Additionally, we observed an increase in the expression of IRF9 and STAT2 of the IFN signalling pathway within the paediatric diffuse glioma cell lines, suggesting activation of an inflammatory stress response shown to decrease chemosensitivity in small cell lung cancer cells." (PMID 36010867, 2022).
Stroke (2 papers, 2014). Sudden impairment of blood flow to a part of the brain due to occlusion or rupture of an artery to the brain. "An increased expression of the newly identified stroke genes Il6ra, Il6st, S100a4, Stat1, and Stat2, but also the known genes Col1a1, Col1a2, Col3a1, has been implicated in blood vessel remodeling and contributes to vascular rarefaction, leakage, and intracranial aneurysms." (PMID 24672479, 2014). "Stat1 and Stat2 are new players in the stroke search for novel therapeutic targets." (PMID 24672479, 2014). "STAT1 and STAT2 are reported to be involved in signaling responses to interferon; their reduction in multiple EA treatment might contribute to anti-inflammation against the secondary injury after stroke." (PMID 25126102, 2014).
type 1 diabetes (2 papers, 2013 to 2022). "Our data provide additional details regarding the IFN-α-signaling pathway during type I diabetes based on the use of antibodies to label proteins downstream of IFNAR1, such as STAT1, STAT2, AKT, and IκB-α." (PMID 23533683, 2013).
ulcerative colitis (2 papers, 2020 to 2022). An inflammatory bowel disease involving the mucosal surface of the large intestine and rectum. "In particular, Mahuang tang and Yinqiao powder antagonized acute upper respiratory tract infection by activating STAT2, resulting in improving the immune barrier function of mouse nasal mucosa, whereas, Si-Ni-San inhibited STAT2 activation for alleviating ulcerative colitis (UC)." (PMID 36324680, 2022).
Werner syndrome (2 papers, 2018 to 2021). "We show that unphosphorylated STAT1 and STAT2 protein levels are increased in NHDFs after in vitro cellular aging as well as in fibroblasts from a patient with Werner syndrome, which leads to premature aging." (PMID 30455980, 2018). "Therefore, the increased ISG expression in cells from a patient with Werner syndrome may be independent of phosphorylated STAT1 and STAT2, similar to the case in senescent NHDFs." (PMID 30455980, 2018).
Acute hepatitis (1 paper, 2018). Acute hepatic injury resulting from inflammation typically accompanied by increased serum alanine transaminase activity. "Based on the limited data available from human cases of RVF, and studies using other animal models for aerosol RVFV infection, acute hepatitis during RVFV infection is a common finding and our study suggests that STAT2 KO hamsters develop similar inflammatory liver lesions." (PMID 30463176, 2018).
age (1 paper, 2018). A temporal measurement of the time period elapsed since an identifiable point in the life cycle of an organism. "Further elucidation of the roles of STAT1 and STAT2 may enable development of chemotherapeutic agents to prevent aging and/or age-related pathologies." (PMID 30455980, 2018).